THBS2 (thrombospondin 2)
Diseases named in the same sentence as THBS2 in open-access papers (continued):
Sharing a sentence is not in itself a finding about the gene and the disease.
tumor (continued). "Six tumor antigens (THBS2, FSTL3, TNNT1, BGN, CTHRC1, and NOX4) were identified as potential therapeutic candidates for the anti-CRC mRNA vaccine that can be processed and presented by APCs to activate a robust immune response." (PMID 35127707, 2021). "FN1, ITGA5, THBS2, and LAMA1 were associated with cell adhesion and metastasis, and the expression of TGFB1, COL4A1, COL4A2, and THBS2 inhibited tumor growth." (PMID 34370778, 2021). "Thbs1 and Thbs2 have been well acknowledged as potent endogenous inhibitors of angiogenesis and tumor growth." (PMID 33154757, 2020). "The quantification results suggested that COL1A1, COL3A1, SPP1, and THBS2 protein levels were significantly increased in GC tumor tissues compared to normal adjacent tissues." (PMID 33665169, 2020). "In this study, we first found that THBS2/TLR4 interaction promotes the tumor growth of CRC by enhanced HIF-1α-mediated glycolysis." (PMID 33244454, 2020). "According to this study, meta-analysis of GEO and TCGA datasets showed the relation between THBS2 expression level with tumor metastasis and prognosis." (PMID 33585016, 2020). "In vitro experiments demonstrated that the knockdown or overexpression of THBS2 impairs or enhances the proliferation of tumor cells." (PMID 33244454, 2020). "The in vivo experiment indicated that blocking THBS2/TLR4 interaction significantly extends the survival of tumor-bearing mice." (PMID 33244454, 2020). "Studies have shown that THBS2 plays an important role in tumours and is related to the degree of malignancy." (PMID 32319226, 2020). "Genes such as INHBA, IGF2, LGALS1, RHOJ, and THBS2 were upregulated in the tumor buds but downregulated in the microenvironment." (PMID 28687755, 2017). "Then, the serum RBP4 and THBS2 concentrations were graded according to the 7th edition of the International Union against Cancer (UICC) tumor node metastasis (TNM)." (PMID 29190912, 2017). "Datasets GSE41328, TCGA, GSE32323 and GSE31737 showed that THBS2 was higher expression in tumor tissue when compared with paired adjacent normal tissue." (PMID 27632935, 2016). "An immunohistochemical study showed that THBS2 expression levels were significantly correlated with the tumor size and stage." (PMID 27513329, 2016). "The present study demonstrated that THBS2 and its coexpressed genes were involved not only in tumor-related ECM proteins, but also immune-related bioprocesses." (PMID 27513329, 2016). "Differences were observed for the known tumour markers Thrombospondin-2, Estrogen-receptor and Her2, and the levels of the central regulatory JNK/SAPK kinase decreased." (PMID 27659302, 2016). "We found that THBS2 was significantly up regulated in tumor tissue when compared with paired adjacent normal tissue." (PMID 27632935, 2016). "The expression level of THBS2 showed a gradually increasing trend from distant tissues, adjacent stroma to tumor epithelium." (PMID 27632935, 2016). "Our study suggested the high level of THBS2 expression serves as a significant role in CRC progression through promoting tumor growth and accelerating tumor cell metastasis." (PMID 27632935, 2016). "THBS2 and coexpressed genes were identified in this study and the gene products are highly involved in tumor-related bioprocesses." (PMID 27513329, 2016). "• Thrombospondin 2, a potent inhibitor of tumor growth and angiogenesis and a matricellular glycoprotein which mediates cell-to-cell interaction." (PMID 22530940, 2012). "Both genes, thrombospondin-2 and procollagen V-alpha 2 showed the highest level of mRNA in the human liver invasion compartment and the murine tumor invasion compartment respectively." (PMID 18823562, 2008). "Of these probe sets, several genes encoding proteins involved in extracellular matrix (ECM)-tumor interaction and focal adhesion (COL6A3, COL8A1, CTHRC1, THBS2, COMP) were upregulated, whereas ITGA2gene with the same function was downregulated in tumor cells." (PMID 17389037, 2007).
tumor (continued). "THBS2, an ECM glycoprotein, has also been implicated in modulating tumor angiogenesis and immune evasion, which may further compromise drug efficacy." (PMID 41291892, 2025). "Applying similar tumor microenvironment oriented analytical strategies to THBS2, CTNNB1, COL4A1, and E2F3 may offer deeper insight into their roles in shaping immune suppression, stromal remodeling, and treatment response in STAD." (PMID 41291892, 2025). "Among these mediators, pigment epithelium-derived factor (PEDF), Thrombospondin 1 (THBS1) and 2 (THBS2) are highly expressed in iCCA tissue, where they act as inhibitors of angiogenesis and promoters of lymphangiogenesis, thereby facilitating tumor cells dissemination." (PMID 40001923, 2025). "Studies indicates that CAF-derived THBS2 promotes tumor growth and adhesion." (PMID 40520886, 2025). "The mouse homolog of thbs2a, Thbs2, is reported to be involved in cell adhesion and migration of mesenchymal cells in mouse, and human THBS2 has been reported to be a tumor suppressor." (PMID 40495676, 2025). "We further analyzed the correlation between the changes in ALPPL2+ and THBS2+ exosome concentration throughout the treatment course with the changes in tumor size using linear mixed models in individual patients grouped by CA19-9 status (elevated, non-elevated, and all subjects)." (PMID 40897818, 2025). "RNA in situ hybridization revealed that cancer-associated fibroblasts (CAFs), not tumor cells, express THBS2, with levels increasing as the disease progresses in mouse models." (PMID 41373732, 2025). "COL4A1 and THBS2 showed strong positive correlations with immunosuppressive cells, such as macrophages and myeloid-derived suppressor cells (MDSCs), reinforcing their potential role in establishing an immune-tolerant tumor microenvironment." (PMID 41291892, 2025). "THBS2, secreted by not only cancer cells but also endothelial cells and immune cells, plays an important role in cancer progression, though serving as either a tumour-suppressor or tumour-promoter remains controversial." (PMID 38035445, 2024). "THBS1, THBS2, and PEDF reduce angiogenesis and promote tumor-associated lymph angiogenesis in iCCA." (PMID 39040110, 2024). "Despite THBS1 and THBS2 possibly having variable effects on tumor cell adhesion and migration, in the TME, they often behave as adhesive and chemotactic proteins by binding several members of the integrin family through the TSR1s, TSR12s, TSR3s, and the N-terminal domains." (PMID 38339060, 2024). "THBS2 may also affect the differentiation and infiltration of tumors by inhibiting the formation of tumor blood vessels." (PMID 36842141, 2023). "The increased expression of FOXQ1, and THBS2 is explained by ectopic expression in CC-tumor cells." (PMID 38156105, 2023). "Recent studies have found that THBS2 promotes tumor progression." (PMID 35879877, 2023). "Moreover, miR-203a-3p can act as a tumor suppressor gene by downregulating insulin growth factor 1 receptor and thrombospondin 2 expression, suppressing metastasis and invasion, and enhancing drug sensitivity." (PMID 37762343, 2023). "Since FOXQ1 and THBS2 were ectopically expressed in CC tumor cells it was of interest to compare their expression with other ectopically expressed biomarkers like the chemokines CXCL16 and CXCL17 particularly since these two chemokines were associated with bad prognosis." (PMID 38156105, 2023). "Finally, H&E staining showed that mice bearing sh-AGAP2-AS1-treated ACHN cells had fewer lung metastasis tumor nodules, while the tumor nodules metastasized to the lung tissue of nude mice bearing sh-AGAP2-AS1 + oe-THBS2-treated ACHN cells increased." (PMID 38110984, 2023). "To verify whether THBS2 is involved in the inhibitor effects of MSCs-EVs-encapsulated miR-598 on the tumor growth and metastasis of NSCLC, we conducted subcutaneous tumorigenesis experiments in nude mice." (PMID 36609437, 2023).
tumor (continued). "Also, THBS2, a mediator of cell-cell and cell-matrix interactions, which suppresses angiogenesis and tumor growth, was downregulated in the co-culture conditions." (PMID 36868311, 2023). "Accordingly, Thbs2 is deeply involved in the proliferation, migration, and invasion of tumor cells." (PMID 37667335, 2023). "Similarly, THBS2 mediates cell-to-cell and cell-to-matrix interactions and promotes tumor progression." (PMID 37444464, 2023). "Studies have shown that thrombospondin-2 (TSP2) may be closely related to tumour occurrence and development." (PMID 35255858, 2022). "The aim of this study was to reveal the relationship between THSB2 expression and prognosis of tumor patients, and the interaction of THBS2 expression with immune cell infiltration and extracellular matrix proteins, providing further insights into cancer prevention and treatment targets." (PMID 35701829, 2022). "The role of THBS2 in prognosis may be driven by an interaction with the extracellular matrix, enabling tumor progression and metastases." (PMID 36222710, 2022). "In pancreatic cancer, SHh indirectly promotes tumor angiogenesis by inducing Ptch1 and Gli1, thereby inhibiting two enriched stroma-derived antiangiogenic factors (THBS2 and TIMP2), and directly promotes tumor angiogenesis by activating small GTPases of the RHO family in the presence of VEGF." (PMID 36517618, 2022). "In addition, THBS2 expression positively correlated with tumor-promoting immune infiltrating cells and negatively correlated with tumor-suppressing immune infiltrating cells." (PMID 35701829, 2022). "Secondly, THBS2 may affect the progression and prognosis of GC by changing the tumor microenvironment and may be a potential therapeutic target for GC." (PMID 35186032, 2022). "Thrombospondin-2 (THBS2) is a versatile glycoprotein that regulates numerous biological functions, including the apoptosis-proliferation balance in endothelial cells, and it has been linked to tumor angiogenesis." (PMID 35701829, 2022). "Because THBS2 is a protein secreted by CAFs into the tumor microenvironment and correlates with tumor recurrence, we treated cancer cells with exogenous recombinant THBS2 protein to mimic the effect of THBS2 on LUAD cancer cells and T cells isolated from a LUAD patient." (PMID 35547750, 2022). "Together, these results suggest that THBS2 could act as a tumor activator for the growth and metastasis of TNBC cells." (PMID 36405394, 2022). "Our previous proteomic study has indicated that THBS2 was highly expressed in TNBC tumor tissues." (PMID 36405394, 2022). "These lines of evidence support the idea that THBS2 might facilitate tumor recurrence and metastasis, in part, by promoting the escape of immune surveillance in LUAD." (PMID 35547750, 2022). "Additionally, high thrombospondin 2 (THBS2)-expressing cancer cells are also more efficient on activating lung fibroblasts, which subsequently induce the transition of tumor cells into a more epithelial phenotype." (PMID 34201840, 2021). "THBS2 is an effective inhibitor of tumor growth and angiogenesis." (PMID 34094925, 2021). "Our experiments further suggest that THBS2 is involved in tumor metastasis by enhancing EMT." (PMID 34804159, 2021). "Clinically, THBS2 deficiency is also correlated with low HCC survival, where high levels of CSCs with low THBS2 expression in HCC are associated with decreased collagen fiber deposits and an invasive tumor front." (PMID 33717837, 2021). "THBS2 shows the potential ability to enhance EMT, which is critical in tumor metastasis, indicating that THBS2 may be involved in tumor metastasis." (PMID 34804159, 2021). "In addition, a novel tumor marker, “thrombospondin-2”, has been noted for its high detection rate for PDAC." (PMID 34439375, 2021). "Our experiments further verified that THBS2 participates in tumor metastasis by enhancing EMT." (PMID 34804159, 2021).
tumor (continued). "Similarly, the analyzed clinical information shows that patients with higher expression of THBS2 tend to have a larger tumor size, higher T stage, and lower survival rate." (PMID 33244454, 2020). "Increasing the THBS2 expression in cancer inhibited tumor growth." (PMID 31612481, 2020). "Distinguished with VCAN and THBS2, though DCN was associated with the extracellular matrix, it could antagonize many tyrosine kinase receptors to inhibit tumor development and progression." (PMID 33200655, 2020). "Transcriptome analysis of sorted MC-38 tumor cells revealed upregulation of vessel-stabilizing factors such as endostatin, Pdgfa, Thbs2 in HIF-1α-KD cells and reduced expression of pro-angiogenic factors such as Cyr61, Cox-2 and Angptl4 when compared to Mock tumors." (PMID 33142239, 2020). "Furthermore, the expression circ_0020123 and THBS2 was decreased, while the miR-590-5p was increased in xenograft tumor transfected with sh-circ_0020123." (PMID 32831647, 2020). "Thrombospondin 2 (THBS2) was found to repress tumor growth and angiogenesis." (PMID 31671866, 2019). "Thrombospondin-2 (THBS2) is a secreted protein overexpressed in numerous cancers and may function as a diagnostic tumor marker." (PMID 31296790, 2019). "In a recent study comparing the matrsiome of MDA-WT and MDA-Lung tumour xenografts, MMP1 and THBS2 were detected uniquely in MDA-WT tumours and AGRN was detected uniquely in MDA-Lung tumours, which correlates with our proteomics data of MDA-WT and MDA-Lung secretomes." (PMID 31160380, 2019). "Recently, a novel tumor marker, thrombospondin-2 (THBS-2), has been produced." (PMID 29439461, 2018). "In contrast, staining for THBS2 was seen in both the tumor and the stroma." (PMID 29176937, 2017). "Interestingly, increased mRNA expression was already observed in normal tissue of tumor patients compared to healthy donors for THBS2, SPARC, LTBP2 as well as the collagens COL8A1 and COL12A1." (PMID 29176937, 2017). "Increasing the expression levels of THBS1 or THBS2 in tumor tissue can inhibit tumor growth." (PMID 29190912, 2017). "The diminished expression of THBS2 leads to increased accumulation of matrix metalloproteinase 2 and ultimately influences cellular density and extracellular matrix structure, thereby resulting in tumor progression." (PMID 28036291, 2017). "Thrombospondin-2 is considered a potent endogenous inhibitor of tumor growth and angiogenesis." (PMID 28743863, 2017). "Moreover, THBS2 was higher expression in tumor budding, which was considered as the cells with EMT phenotype." (PMID 27632935, 2016). "As another member of thrombospondin family, THBS2 may be a potential inhibitor of tumor growth and angiogenesis." (PMID 27716259, 2016). "THBS2 was over expressed in tumor when compared with paired normal tissues." (PMID 27632935, 2016). "The results showed that the expression of THBS2 in tumor budding was significantly increased that may closely related with tumor metastasis and prognosis." (PMID 27632935, 2016). "In addition, there was a significant positive correlation between THBS2 expression and the tumor TNM grade (P = 0.001)." (PMID 27632935, 2016). "The results may shed light on the role of THBS2 in the tumor microenvironment during the progression of lung AC." (PMID 27513329, 2016). "A truncated-recombinant THBS2 protein inhibited tumor growth and angiogenesis in vivo." (PMID 27513329, 2016). "THBS2, whose expression is up-regulated by ectopically expressed miR-34b, was chosen because it has previously been suggested to modulate cell adhesion and migration and because it can act as a potent endogenous inhibitor of tumor growth and angiogenesis." (PMID 21949788, 2011). "Therefore, we hypothesized that RP11-417E7.1/THBS2 signaling may promote tumor cell secretion of THBS2 into the TME in the form of exosomes, thereby inducing M2 macrophage polarization in CRC." (PMID 39020380, 2024).
tumor (continued). "Furthermore, we attempted to investigatee whether miR-598 secreted by MSCs-EVs influenced the tumor metastasis of NSCLC function through the involvement of THBS2." (PMID 36609437, 2023). "Therefore, in this study, we investigated whether upregulation of THBS2 in tumour cells exerts similar effects on macrophages." (PMID 37884956, 2023). "Furthermore, inhibition of THBS-1 promoted angiogenesis and tumor growth of colon carcinoma xenografts, and the expression of THBS-2 in CRC is correlated with inhibition of angiogenesis and lower hepatic metastasis, highlighting the importance of ECM regulation to impair tumor progression." (PMID 35053521, 2022). "Our findings suggested that THBS2 might promote cancer progression by remodeling the tumor microenvironment, affecting CD47-mediated signaling pathways, activating the pro-tumor functions of a disintegrin and metalloproteinase with thrombospondin motifs, and enhancing MMP-2 expression." (PMID 35701829, 2022). "Therefore, we speculated that the high expression of THBS2 might affect the disease progression and prognosis of patients with GC by inducing changes in the tumor microenvironment." (PMID 35186032, 2022). "THBS2 might play a pleiotropic role in modulating cancer cells and particularly tumor immunity." (PMID 35547750, 2022). "We also demonstrated that THBS2 downregulation in HCC is tightly associated with adverse HCC survival and that high CD133/low THBS2 expression in HCC specimens correlates with decreased collagen fiber deposits and invasive tumor fronts, which supports our functional findings in vitro and in vivo." (PMID 33717837, 2021). "Finally, suppression of circ_0020123 inhibited tumor growth in vivo through miR-590-5p/THBS2 axis." (PMID 32831647, 2020). "Therefore, THBS2 plays a tumor-promoting role in CRC development." (PMID 33244454, 2020). "Moreover, THBS2 promotes tumor progress, including cell proliferation, migration, and invasion." (PMID 33244454, 2020). "Notably, the role of THBS2 in tumor cells has received more and more attention." (PMID 31296790, 2019). "Moreover, based on the effects of THBS2 on tumour development and angiogenesis, our researches provide valuable clues for clinical practices to develop molecular inhibiting therapeutics using targets deduced from the biological knowledge provided by the THBS2 signature." (PMID 25262009, 2014). "All four candidate genes (THBS2, FN1, COL1A1, COL5A1) were found to be upregulated in tumour samples compared to matched normal samples in our microarray analysis." (PMID 40860666, 2025). "Promoter methylation analysis using the UALCAN database revealed that THBS2, CTNNB1, COL4A1, and E2F3 exhibited significantly lower promoter methylation levels in STAD tumor tissues compared to normal controls." (PMID 41291892, 2025). "In CRC, the COL11A1 gene is excessively expressed and contributes to tumor advancement by upregulating other genes like THBS2, COL10A1, COL5A2, and COL1A2, thereby driving neoplasia." (PMID 40109582, 2025). "While the enrichment of ECM-related pathways is in line with the known roles of THBS2, FN1, COL1A1, and COL5A1 in extracellular matrix remodelling and tumour progression, the concurrent upregulation of mTOR signalling presents an intriguing finding." (PMID 40860666, 2025). "The mRNA expression analysis revealed that THBS2, CTNNB1, COL4A1, and E2F3 were significantly upregulated in tumor tissues compared to normal gastric tissues in the TCGA-STAD cohort." (PMID 41291892, 2025). "In the iCCA, PEDF along with THBS1 and THBS2 are expressed and released in the TME, where they play a role in the tumor progression." (PMID 40001923, 2025). "While THBS1 and THBS2 also directly promote iCCA cell proliferation, adhesion and motility, in the present research we demonstrated that PEDF exhibits a tumor suppressor activity on iCCA cell lines by inhibiting their migration and invasion." (PMID 40001923, 2025).